RFX2 (regulatory factor X2)
Description:
Transcription factor that acts as a key regulator of spermatogenesis. Acts by regulating expression of genes required for the haploid phase during spermiogenesis, such as genes required for cilium assembly and function (By similarity). Recognizes and binds the X-box, a regulatory motif with DNA sequence 5'-GTNRCC(0-3N)RGYAAC-3' present on promoters. Probably activates transcription of the testis-specific histone gene H1-6 (By similarity).
Synonyms: FLJ14226
Tractability: PROTAC: ubiquitination databases record sites on it.
Gene: Protein-coding gene on chromosome 19 (5,993,164 to 6,199,572, reverse strand). Ensembl gene ENSG00000087903.
Subcellular location: Nucleus; Cytoplasm
Subcellular location (Human Protein Atlas): Golgi apparatus; Nucleoplasm; Basal body; Cytosol; Primary cilium
Gene Ontology:
Molecular function: protein binding; sequence-specific double-stranded DNA binding; DNA binding; DNA-binding transcription factor activity; DNA-binding transcription factor activity, RNA polymerase II-specific; RNA polymerase II cis-regulatory region sequence-specific DNA binding; DNA-binding transcription activator activity, RNA polymerase II-specific; RNA polymerase II transcription regulatory region sequence-specific DNA binding
Biological process: acrosome assembly; cilium assembly; regulation of transcription by RNA polymerase II; spermatid development; positive regulation of transcription by RNA polymerase II; regulation of DNA-templated transcription
Cellular component: chromatin; cytoplasm; nucleus
Genetic constraint (gnomAD): Loss-of-function variants: 18 observed, 72.41 expected, observed/expected ratio (o/e) 0.25, 90% interval 0.17 to 0.37. The upper end of that interval is the gene's LOEUF score, 0.37, which puts it in group 1 of 6, group 1 being the genes least tolerant of losing a copy. Missense variants: 764 observed, 950.28 expected, observed/expected ratio (o/e) 0.8, 90% interval 0.76 to 0.85. Synonymous variants: 396 observed, 404.73 expected, observed/expected ratio (o/e) 0.98, 90% interval 0.9 to 1.06.
Homologues: Orthologues: macaque RFX2 (99% identical), chimpanzee RFX2 (98% identical), dog RFX2 (94% identical), pig RFX2 (93% identical), mouse Rfx2 (88% identical), rat Rfx2 (87% identical), guinea pig RFX2 (86% identical), tropical clawed frog rfx2 (79% identical), rabbit RFX2 (78% identical), zebrafish rfx2 (75% identical), Drosophila melanogaster Rfx (44% identical). Paralogues in human: RFX3 (66% identical), RFX1 (57% identical), RFX4 (25% identical), RFX6 (25% identical), RFX7 (19% identical), RFX8 (13% identical), RFX5 (12% identical).
Diseases named in the same sentence as RFX2 in open-access papers:
RFX2 is named in the same sentence as 26 diseases in open-access papers, as found by Europe PMC text mining. Sharing a sentence is not in itself a finding about the gene and the disease. The quoted sentences say what the papers report.
ciliopathy (5 papers, 2014 to 2024). A genetic disorder of the cellular cilia or the cilia anchoring structures, the basal bodies, or of ciliary function. "Additionally, we found that Rfx2 directly controls expression of genes encoding axonemal dynein subunits, components of the transition zone, and a component of the BBSome, and many of these genes are mutated in human ciliopathies." (PMID 24424412, 2014). "Ciliary alterations (like in RFX2 -/-) therefore seem to produce a relatively mild phenotype (as it frequently is the case in ciliopathies), where neurons differentiate like in WT, but with a different timing, which may disrupt critical spatiotemporal aspects of brain formation." (PMID 38413974, 2024). "We identified 10 genes (STK38L, TUBB2A/B, CCNO, ARL13B, RFX2, RAB23, TUBA1C, CEP170B, and SPATA7) that are established or candidate ciliopathy genes." (PMID 34485842, 2021). "Hence Rfx2-/- mice do not exhibit the ciliopathy hallmarks observed in Rfx3-/- mice or other phenotypes observed for Rfx-deficient mice." (PMID 26162102, 2015).
breast carcinoma (4 papers, 2021 to 2023). "MECOM and FLI1 activities were decreased, while breast cancer promoted FOSB and RFX2 activities." (PMID 37153595, 2023).
COVID-19 (2 papers, 2022 to 2023). A disease caused by infection with severe acute respiratory syndrome coronavirus 2. "We constructed a 3-gene signature consisting of ARG1, GIMAP7, and RFX2 models for the assessment of COVID-19 severity and prognosis, and found that they are associated with neutrophils, T cells, and hematopoietic stem cells, respectively." (PMID 36352845, 2022). "We constructed a 3-gene signature consisting of ARG1, GIMAP7, and RFX2 for the assessment of COVID-19 severity and prognosis, and determined the cell-specific expression of these genes." (PMID 36352845, 2022). "To further explore the functional and clinical value of ARG1, GIMAP7, and RFX2, we analyzed the Bonn cohort, which included peripheral blood scRNA-seq data from 19 control and 22 COVID-19 patients." (PMID 36352845, 2022). "A LASSO regression classification model composed of ARG1, GIMAP7, and RFX2 was constructed, which could be used to distinguish the severity of COVID-19." (PMID 36352845, 2022). "For example, RFX2 and RFX3 were activated in ciliated cells under all three conditions, but the majority of targets were downregulated in mild/moderate COVID-19 patients compared to healthy cells." (PMID 37936693, 2023). "Regulators RFX2 and RFX3 were shared between healthy individuals and COVID-19 patients, but the two regulators showed different target genes or target expression levels in the two sample types." (PMID 37936693, 2023). "For example, RFX2 and RFX3 showed high activity in ciliated cells regardless of disease severity, while XBP1, NR2F6, SPDEF, and ELF3 were preferentially activated in goblet cells in patients with severe COVID-19, and KLF5 and STAT2 were coactivated in patients with mild/moderate COVID-19." (PMID 37936693, 2023).
ependymoma (2 papers, 2021 to 2022). A WHO grade II, slow growing tumor of children and young adults, usually located intraventricularly. "Interestingly, FGFRi treatment resulted in induction of astroependymal-like signatures as well as FOXJ1 and RFX2, both factors associated with a more differentiated ependymal-like cell state in brain development and ependymoma." (PMID 34046693, 2021). "The expression of RFX2 and FOXJ1 in ependymomas is higher than that in normal tissues and other brain tumors such as astrocytomas." (PMID 35087169, 2022).
leukemia (2 papers, 2019 to 2023). A malignant (clonal) hematologic disorder, involving hematopoietic stem cells and characterized by the presence of primitive or atypical myeloid or lymphoid cells in the bone marrow and the blood. "We also detected the genes CATSPERD, PRR22, RFX2, and MILT1, which have been shown to be associated with leukemia." (PMID 31013791, 2019).
lung carcinoma (2 papers, 2022 to 2023). "HOXC6 and RFX2 are also deregulated in eight sets of lung cancer as FOXF1 and none of the other types of cancer." (PMID 36101460, 2022).
breast tumors (1 paper, 2015). "Candidates that exhibited the strongest association with breast tumors were regions from the longest introns of RFX2, EPAS1, RBMS1, ZEB2, and the three different introns of CRIM1." (PMID 25798919, 2015).
cyst (1 paper, 2007). A sac-like closed membranous structure that may be empty or contain fluid or amorphous material. "In zebrafish, Rfx2 is expressed specifically in multiciliated cells of the pronephros and loss of Rfx2 leads to cyst formation and loss of multicilia." (PMID 17875208, 2007).
glioblastoma (1 paper, 2022). The most malignant astrocytic tumor (WHO grade IV). "In addition, RFX2 is reported to be involved in the regulation of the promoter of fibroblast growth factor-1B, a major transcript within the human brain and retina, by forming a complex with RFX3 in human glioblastoma cells, suggesting that RFX2 alone is insufficient for its regulation." (PMID 35714115, 2022).
Infertility (1 paper, 2015). "The morphology of the mutant and characterization of RFX2-regulated pathways may provide a useful basis for assigning genetic causes to human infertility, and ultimately for deciphering the regulatory networks that direct sperm formation." (PMID 26162102, 2015).
intellectual disabilities (1 paper, 2021). "Besides, the sequence alterations of RFX2 may cause various intellectual disabilities, heart anomalies, renal defects, otologic disorders, and abnormal growth of ectodermal appendages, including teeth." (PMID 35145545, 2021).
migraine (1 paper, 2018). "Six6 is associated with a hereditary disorder of the eye that presents with migraine symptoms and decreased expression of Rfx2 elicited increased sensitivity in a model of neuropathic pain." (PMID 30618656, 2018).
primary ciliary dyskinesia (1 paper, 2015). A rare, genetically heterogeneous, primarily respiratory disorder characterized by chronic upper and lower respiratory tract disease. "Among 32 genes in which defects lead to primary ciliary dyskinesia, six (Dnaic2, Ccdc40, Armc4, Ccdc164/DRC1, Rsph9, Ccdc11) are strongly downregulated in Rfx2-/- testes at both time points, and three others only at P30 (Ccdc65, Zmynd10, Ccno)." (PMID 26162102, 2015).
pulmonary fibrosis (1 paper, 2022). Chronic progressive interstitial lung disorder characterized by the replacement of the lung tissue by connective tissue, leading to progressive dyspnea, respiratory failure, or right heart failure. "Next, we examined the gene and protein expression of Rfx2, one of three common upregulated genes among the three combinations of nintedanib- and vehicle-treated mice based on progression of pulmonary fibrosis (Rfx2, Hspa1a, and Hspa1b), and Bmpr2." (PMID 35714115, 2022). "In the present study, fewer upregulated genes than downregulated genes were detected, and among the 3 combinations of nintedanib- and vehicle-treated mice based on the progression of pulmonary fibrosis, only three common upregulated genes were identified (Rfx2, Hspa1a, and Hspa1b)." (PMID 35714115, 2022).
Sepsis (1 paper, 2021). Sepsis is defined as life-threatening organ dysfunction caused by a dysregulated host response to infection. "Our results give direction on how sepsis master regulators work coordinately in disease progression, especially MEF2A, TRIM25, and RFX2, with potential implications in pediatric sepsis prognosis." (PMID 34680414, 2021).
small cell lung carcinoma (1 paper, 2022). Small cell lung cancer (SCLC) is a highly aggressive malignant neoplasm, accounting for 10-15% of lung cancer cases, characterized byrapid growth, and early metastasis. "RFX2 (regulatory factor X2) is overregulated in small-cell lung cancer, and it is related to chemoresistance." (PMID 36101460, 2022).
tooth agenesis (1 paper, 2021). A tooth disease characterized by failure to develop one or more missing teeth. "Hence, the RFX2 variant is the most likely candidate causing non-syndromic tooth agenesis." (PMID 35145545, 2021).
tumor (6 papers, 2015 to 2023). "In our data, the expression of epithelial cilium movement markers, including FOXJ1, PRG, RFX2, and TMF1, although increased during the process, were mainly overexpressed in primary tumor cells." (PMID 35935940, 2022). "A relationship between tumor immune cells and angiogenesis in KIRC samples' data obtained from TCGA was studied, and RFX2, SOX13, and THRA were identified as the top three MTF in regulating angiogenesis signature in KIRC patients." (PMID 35096203, 2022). "Consistent with the observed down-regulation of RFX2, ZEB2, and CRIM1 regions using qRT-PCR, in-situ hybridizations with probes corresponding to these genomic loci clearly reveal that these loci are down-regulated in tumor epithelium." (PMID 25798919, 2015). "The expression of RFX2 is negative in NSCLC and its subtypes’ datasets but positive in the SCLC dataset, which suggests its function could be that of a tumor suppressor in NSCLC and that of an oncogene in SCLC." (PMID 36101460, 2022).
infection (2 papers, 2023 to 2024). The state of being infected such as from the introduction of a foreign agent such as serum, vaccine, antigenic substance or organism. "At 3 days post-infection (DPI 3), we confirmed the successful overexpression of RFX2, RFX3, RFX4, and RFX5 in stem cells." (PMID 38386071, 2024).
RFX2 also shares sentences with these, for which no sentence is quoted: cancer (3 papers); autism (1); brain tumors (1); cerebral palsy (1); dyslexia (1); pulmonary hypertension (1); renal carcinoma (1).